TLR9 (toll like receptor 9)
Diseases named in the same sentence as TLR9 in open-access papers (continued):
Sharing a sentence is not in itself a finding about the gene and the disease.
infection (continued). "In addition, the recognition of microbial DNA by TLR9 is an essential component of the innate immune response to infections, and it has been shown that human neutrophils express TLR9." (PMID 24987851, 2014). "TLR9-/- AMs infection with the ΔPscf mutant induced both TNFα and IL-6 but failed to induce IL-1β." (PMID 24595157, 2014). "However, at 24 hours after infection, these levels were detected in BALs of TLR9-/- mice at much lower levels compared to those observed in BALs of WT mice." (PMID 24595157, 2014). "To examine whether infection of macrophages with B. anthracis spores increases TLR9 mRNA expression, we infected RAW264.7 cells with B. anthracis spores (MOI of 10) for various time periods and then examined TLR9 mRNA expression using real-time RT-PCR." (PMID 25472474, 2014). "However, at 24 hours post-infection, the bacterial load was significantly decreased in TLR9-/- compared to WT mice." (PMID 24595157, 2014). "This is relevant because the strong expression of TLR9 may increase the sensitivity of CpG-DNA recognition, and the phagocytosis of H. pylori, increasing the inflammatory response during infection." (PMID 23755130, 2014). "Our experimental data clearly supported a role for the innate immune system and MyD88-dependent signaling pathways in the development of resistance to infection with L. guyanensis, and also implied a partial role for the MyD88 dependent, TLR9 signaling pathway." (PMID 24801628, 2014). "Following infection with P. aeruginosa, a significant increase in both NO production and the inducible nitric oxide synthase (iNOS) mRNA was detected in AMs derived from TLR9-/- compared to WT mice." (PMID 24595157, 2014). "Furthermore, during infection, the release of DNA from P. brasiliensis is expected to occur following fungal cell death, thus suggesting that TLR9 activation in vivo is very likely to happen." (PMID 23936560, 2013). "It will be important to determine whether TLR7- and TLR9-driven activation of pDC plays any role in immune activation in the chronic stages of infection when disease is manifest." (PMID 23935491, 2013). "Several lines of evidence suggest that TLR9 may play a role in infection by P. brasiliensis, similarly to what is already described for other pathogenic fungi, such as A. fumigatus, C. albicans and C. neoformans." (PMID 23936560, 2013). "Furthermore, the role of TLR9 is amplified in DCs during the infection which contrasts with the dramatically decreased capacity of the macrophage/monocyte lineage to respond to TLR9 agonist." (PMID 23650544, 2013). "To assess the role of TLR9 in P. brasiliensis infections, we used in vivo models of infection." (PMID 23936560, 2013). "In contrast, during 24 hours of RSV infection, the levels of TLR3-4 and TLR7-8 were increased from 3 h after RSV infection, and reached to the highest levels at 24 h after infection, whereas TLR9 expression reached a peak level at 12 h after infection with RSV, and then declined." (PMID 24039959, 2013). "Indeed, upon transient neutrophil depletion, TLR9−/− mice survived during the first 48 hours post-infection, resembling the phenotype of WT mice." (PMID 23936560, 2013). "The differential use of TLR2 and TLR9 by the immune cells during the acute phase of the infection explains why TLR9- but not TLR2-deficient mice are susceptible to T. cruzi infection." (PMID 23650544, 2013). "As our results show, TLR9 is crucial for mice survival in early times of infection (first 48 h)." (PMID 23936560, 2013). "However, on day 21 after P. acnes priming we observed significantly enhanced resistance to Salmonella serovar Typhimurium in TLR9−/− mice, while in wt mice the resistance to infection returned to the pre-priming level." (PMID 22745710, 2012).
infection (continued). "Neutrophils are attracted to the infected tissue by chemokines such as KC or MIP-2, while monocytes are attracted by MCP-1, so we assessed the protein levels of KC, MIP-2 and MCP-1 in the sera of uninfected or MCMV-infected WT or TLR9−/− male and female mice at 36 h upon infection." (PMID 23028824, 2012). "As following TLR3 stimulation, we couldn’t find statistically significant differences in IFN-α production between males and females following TLR9 stimulation or infection with HSV-1." (PMID 22768144, 2012). "In addition, Bafica and colleagues demonstrated that T. cruzi-DNA, a TLR9 agonist, stimulated cytokine production by antigen-presenting cells and cooperatively participated in the control of infection." (PMID 21869919, 2012). "Because there may be some TLR-9-independent signaling that leads to IFN-β production in the lung by day 7 after infection, it is possible that at later time points, sufficient IFN-β may be available to limit fibroproliferation even in TLR-9-/- mice." (PMID 21810214, 2011). "In contrast, pDCs responded to the infection in a manner entirely dependent on TLR9." (PMID 21949653, 2011). "Interestingly, both synergy and co-operation between TLR2 and TLR9 have been observed in response to infection resulting in heightened Th1-like responses." (PMID 21695103, 2011). "This might indicate that the TLR4 signalling pathway may be less affected than the TLR7 and TLR9 signalling in Dogon undergoing infection." (PMID 21483827, 2011). "Because Th2-biased mice are known to be prone to the development of fibrosis in response to infection with γHV68, it was possible that a cytokine imbalance could explain the exacerbation of fibrosis in TLR-9-/- mice." (PMID 21810214, 2011). "Finally, no global differences in lung pathology were observed between lungs of WT and TLR9 knockout mice at day 12 following infection with H99 when the same scoring criteria were applied as for the previous experiment." (PMID 22039448, 2011). "Finally, we examined TLR9 knockout mice using this same infection model to define its specific contribution towards MyD88-dependent pathogenesis in a unified manner." (PMID 22039448, 2011). "Interestingly, the expression of Fizz-1 as a marker of alternative activation or M2 phenotype was found only in macrophages from double mutant mice, suggesting that both TLR4 and TLR9 are required to prevent alternative macrophage activation during infection." (PMID 20360853, 2010). "In addition, it is possible that parasite DNA attached to malarial pigment (haemozoin) produced in the course of infection further activates the innate immune response through TLR-9 engagement." (PMID 20470442, 2010). "In addition to its well-described function in the recognition of CpG motifs, TLR9 has been shown to play an important role in the recognition of parasite DNA and host resistance to infection by several different protozoan parasites." (PMID 20865117, 2010). "Together, these results clearly indicate that deficiency in TLR2, TLR4, TLR9 or even MyD88 expression does not impair CD8+ T cell effector responses during infection with T. cruzi." (PMID 20442858, 2010). "Interestingly, they showed that acute infection is more severe in TLR2−/− TLR9−/− mice than in TLR9−/− mice or either TLR2−/−- or TLR4-deficient mice, albeit not as much as in the overtly susceptible MyD88−/− mice." (PMID 18052532, 2007). "In contrast, CD4+ cells exhibited a down-regulated TLR9 as a consequence of infection." (PMID 16504163, 2006). "Hence, detecting the copy number of mtDNA bound by red blood cells through TLR9 may emerge as a novel indicator for monitoring infection within the body." (PMID 40046178, 2024). "(2016) confirmed the role of TLR9 in the initial protection against P. brasiliensis, showing that immunization of mice with the recombinant protein rPb27 associated with CPG oligodeoxynucleotide motifs provides high protection against the fungus, 30 days after infection." (PMID 38045758, 2023).
infection (continued). "It should be noted that although our study showed that blocking the TLR9-mediated IL-12p40 response ameliorated brainstem encephalitis caused by severe EV71 infection in a mouse model, it is likely that the IL-12p40 response plays a dual role during the infection." (PMID 35399111, 2022). "To assess whether the loss of TLR2 and TLR9 affects host control of bacterial dissemination to organs outside the infected femur, we measured CFU burdens in the contralateral femur, kidneys, and liver over a 14-day time course of infection." (PMID 36226943, 2022). "In this study, we investigate the role of TLR2 and TLR9 signaling in the specific context of posttraumatic S. aureus osteomyelitis with a focus on understanding how these immune receptors influence host antibacterial defenses and modulate infection-induced changes to bone homeostasis." (PMID 36226943, 2022). "The purpose of this study was to carry out for the first time a survey to investigate the already known and de novo SNPs in TMEM154, CCR5, TLR9 and MYD88 target genes in some flocks reared in Italy, in order to identify variants that could confer resistance to SRLVs infection." (PMID 34372496, 2021). "Finally, we examined whether expansion of TER119+CD11a+ cells and TER119+CD11chigh cells was a result of isolated TLR9-ligation with CpG-ODN or would also occur during infection-induced inflammation." (PMID 32849551, 2020). "Hence, TLR9 activation through recognizing self-DNA may help to lower systemic inflammation and inflammatory organ damage depending on the infection." (PMID 33643304, 2020). "Given the criteria above and the fact that YY1 could target TLR7 and TLR9 signaling, type I and II interferon production/pathways, reported as effective for virus clearance during infection, if activated, establishes YY1 as the best TF with the best potential as a drug target for BCoV therapy." (PMID 32872640, 2020). "In the context of infection by P. brasiliensis, the absence of TLR9 increases the susceptibility of mice at the beginning of the infection (48 h), generating an exacerbated inflammatory response with the increased neutrophil influx and high levels of TNF-α at the site of infection." (PMID 33194839, 2020). "Therefore, we analyzed the Th1 cytokine that could be involved in the infection and in the increase of parasite load and lesion size in TLR9-/- mice." (PMID 30802247, 2019). "In the present study we were not able to test for associations between TLR7 or TLR9 and susceptibility to infection due to low variability at these loci, thus we were able to analyse the selection pattern acting on these loci only based on the results of neutrality tests." (PMID 29849060, 2018). "Similarly, combination of CpG-oligo-deoxy-nucleotides, a known TLR9 agonist with recombinant ribosomal antigen L3 or L5 from L. major, improved the protection in two different murine models against homologous challenge infection." (PMID 29312309, 2017). "A more recent study showed that the three nucleic acid sensing TLRs, TLR3, 7 and 9, are crucial for a protective response against L. major infection, as mice which lacked all of these functional TLRs (i.e. TLR3/TLR7/TLR9−/− or UNC93B1−/− mice) were highly susceptible to infection." (PMID 27716391, 2016). "Thus, in that infection model TLR9 may contribute to mouse protection by sensing S. pyogenes DNA by cells other than BMDMs and cDCs, or indirectly, by its known ability to sense self-DNA liberated from dead cells." (PMID 25756897, 2015). "However, increased expression of TLR9 was demonstrated in gastric tissues of patients infected with H. pylori, suggesting an important role of this receptor in the immune response to this infection." (PMID 24987851, 2014).
infection (continued). "The reduced levels of IFN-α observed following infection with UV-VZV might occur through a TLR9-independent mechanism of IFN-α induction, perhaps through the RNA dependent protein kinase (PKR), which was activated following VZV infection and played a role in IFN-α production." (PMID 23061052, 2012). "The quantitative effect of this infection was large, with modelling results indicating that the highest levels of louse reproductive activity (>20 louse egg cases per host) were associated with approximately 50% reductions in TLR2 and TLR9-mediated TNF-α responses." (PMID 19386086, 2009). "However, the differential antibody repertoire induced by TLR7 and TLR9 agonists may have a profound effect on an individual's response to infection and long-term immunity." (PMID 18652679, 2008). "In this small cohort, we only detected positive correlations between platelet-TLR9 and SELP, which was lost with infection." (PMID 40825056, 2025). "infection, several TLRs have been identified, among which TLR-2, TLR-4, and TLR-9 stand out, which are involved in the detection of parasite-derived components and the subsequent activation of the immune response." (PMID 40725420, 2025). "In leukocytes, expression of F13A1 (forming coagulation FXIII) correlated with TLR7, TLR9, RIG-I, MDA5, and LGP2, and with infection the correlations changed to TLR6 and CGAS." (PMID 40825056, 2025). "Specifically, alterations in the expression of these receptors in different regions have been observed during infection, decreasing the transcription of TLR-3, TLR-4, and TLR-9 when the disease progresses." (PMID 40725420, 2025). "As with VV-WR infection, we found a significant increase in the number of ova-specific memory CD8 + T cells following local administration of CpG that was dependent on TLR9." (PMID 38514656, 2024). "Six TLRs recognize the presence of SARS-CoV-2 (TLR2, TLR3, TLR4, TLR7, TLR8, and TLR9), of which TLR2, TLR4, and TLR9 favor the pathogenicity of the virus, while TLR3, TLR7, and TLR8 favor control of the infection and resolution of the disease." (PMID 39062904, 2024). "Interestingly, the available evidence on the TLR-9 function highlighted that, in the setting of H. pylori infection, it might have a dichotomous role, acting as either a promotor or a suppressor of this infection depending on the gastric microenvironment." (PMID 38255710, 2024). "Here, we observed higher TLR2, TLR4, TLR5, TLR6, TLR8, TLR9, Myd88, NLRP3, ASC, and TNF-α mRNA expression at seven weeks after infection by S. mansoni in BALB/c and C57BL/6 mice compared to Swiss mice." (PMID 38896633, 2024). "DNase secretion in the environment or inside host cells can lead to enhanced resistance against the host immune system by escaping the TLR9 recognition system or inducing IFN-1 production by dendritic cells at the infection site." (PMID 39597598, 2024). "Important Toll-like receptors (TLRs), including TLR2, TLR3, TLR4, TLR9, TLR20a, and TLR22, are overexpressed in channel catfish due to infections such as Edwardsiella ictaluri." (PMID 39483482, 2024). "During Leishmania infection, the participation of TLR-9, TLR-4, TLR-2, and TLR-3 is pivotal for mediating a proinflammatory cytokine response and subsequent infection control." (PMID 37111420, 2023). "The level of TLR9 was increased to 747%, p < 0.0001 at 3 h post JEV infection which dramatically increased with increasing time points post infection compared." (PMID 36707891, 2023). "We have demonstrated that LdCen−/− infection specifically upregulates TLR-9 expression and subsequent TLR-9-mediated downstream signaling in DCs compared to LdWT infection." (PMID 37111420, 2023). "We assessed the expression of costimulatory and coinhibitory molecules in LdCen−/− infected DCs under either TLR-9 silenced or JSH-23 treated/untreated conditions and compared them to LdWT infection by flow cytometry." (PMID 37111420, 2023).
infection (continued). "If papillomaviruses indeed interfere with TLR9 activity to promote long-term infections, this raises an important question about what PAMP (pathogen-associated molecular pattern) or DAMP (damage-associated molecular patterns) the cellular TLR9 may be detecting." (PMID 36265836, 2022). "An anti-TLR9 antibody system was employed in conjunction with anti-VGluT1 and anti-GAD67 during separate infections with HHV-6A and HHV-6B." (PMID 35911725, 2022). "Protein analysis showed GLY significantly lowered TLR9 (A, p < 0.05, p < 0.01) protein levels in both B6 and TLR4KO 5 days after infection, respectively." (PMID 36422579, 2022). "The requirement of TLR9 for effective innate immune responses has been reported in a TLR9 deficient mouse model on a BALB/c background that could not elicit an effective Th1 cytokine response after infection with Gram-negative bacterial pathogens such as K. pneumoniae." (PMID 36422579, 2022). "Female C57BL/6 (B6), TLR4 knockout (TLR4KO), myeloid specific TLR4KO (mTLR4KO), their wildtype (WT) littermates, and TLR9 knockout (TLR9KO) mice were infected with P. aeruginosa KEI 1025 and treated with GLY or PBS onto the cornea after infection." (PMID 36422579, 2022). "Several TLRs have been described as important molecules in the resistance to T. cruzi experimental infection, such as TLR2, TLR4, TLR7, and TLR9." (PMID 34336720, 2021). "Signaling via TLR9 is a potent stimulator of cellular immunity, including memory CD8 T cells which are important in bacterial clearance during infection." (PMID 33815413, 2021). "Infections from HSV-1, HSV-2, KSHV, and EBV have been shown to stimulate TLR9-mediated production of type I IFN in pDCs." (PMID 33791247, 2021). "In young adult lung, there was increased expression of Tlr9, Cnpy3, and Ctsb at day 3 post H1N1 or H3N2 infection." (PMID 34829979, 2021). "Recently published experiments showed a recognition of infection with C. diphtheriae by TLR2 and TLR9." (PMID 33805570, 2021). "Some found that, during infection of murine macrophages, TLR2, TLR5, and TLR9 are required for an optimal cytokine response." (PMID 34280250, 2021). "On the other hand, it is possible that the role of TLR9 is redundant with another PRR, involves the production of a cytokine not assayed here, and/or is only evident at a different stage of infection." (PMID 34280250, 2021). "However, TLR9 could conceivably play an indirect role in detecting infection." (PMID 33202596, 2020). "Fourteen-day infection with S. Typhimurium in these pigs increased the relative expression of TLR4 and TLR9 mRNA in the ileum." (PMID 32842482, 2020). "Transcription factors selected as biomarkers for targeting should be predicted for genes such as TLR7, TLR9, RHOA, IRF1, and IL6 since they are activated early in infection." (PMID 32872640, 2020). "In the current study, following infection of rohu with A. invadans, TLR2, TLR3, TLR4 and TLR9 were downregulated." (PMID 33177569, 2020). "As previously reported, MyD88 KO mice did not control LVS infection; further, using this dose and route of infection, LVS control was only modestly dependent on TLR2 and TLR9." (PMID 32745117, 2020). "Survival of mice after a lethal ECTV infection was critically dependent on TLR9, while MVA infection protected mice from ECTV in a manner also dependent on TLR9." (PMID 33092186, 2020). "Many viruses can induce the up-regulation of viperin during infection, and viperin is shown to have critical roles in inhibiting viral replication and facilitating TLR7- and TLR9-mediated production of IFN-I, yet its function can be dampened by some viruses." (PMID 31921110, 2019). "During primary infection, EBV downregulates TLR7, TLR8, and TLR9 expression to support viral replication in infected B cells." (PMID 31238570, 2019). "A similar result has been reported in the HSV genital infection model, as both TLR9 and TLR2 together have been observed to be relevant for resisting intravaginal infection by HSV-1." (PMID 31114761, 2019).